CD4 (CD4 molecule)
Diseases named in the same sentence as CD4 in open-access papers (continued):
Sharing a sentence is not in itself a finding about the gene and the disease.
tumor (continued). "When tumor cells were pre-treated with zebularine, both CD4+ and CD8+ T cells in the co-incubation system proliferated significantly and were more abundant than those in control groups." (PMID 38755254, 2024). "Treatment with anti-CD5 MAb resulted in an increased fraction of CD8+ T cells compared to CD4+ T cell in draining lymph nodes and the tumour microenvironment." (PMID 38487537, 2024). "CD4+ T cells primarily function as helper T cells, supporting anti‐tumor immunity, while CD8+ T cells serve as cytotoxic T lymphocytes, inducing tumor cell apoptosis through diverse pathways." (PMID 38685799, 2024). "Loss of Ccn1 expression by fibroblasts significantly impaired metastasis of tumor cells to lung and increased recruitment of CD4+ T cells into tumors." (PMID 38363129, 2024). "During our analysis of immune cells in the tumor immune microenvironment, we found that CD4+ naive T cells, CD4+ Th1-like cells, and NK cells were significantly downregulated in the high R-loop score group, while CD8+ exhausted T cells were markedly increased." (PMID 39850878, 2024). "Together, these results indicate that bacterial exposure induces a broad MHC II response across lung macrophages, potentially contributing to increased tumor growth through CD4+ T cell activation." (PMID 38570533, 2024). "Targeting these inhibitory mechanisms can selectively induce the upregulation of MHC class II in various AML cell lines, thereby stimulating antigen-dependent CD4+ T cell activation and promoting an effective anti-tumor immune response." (PMID 39538305, 2024). "Activated Th1 responses also promote the activation of M1-like TAMs, CD8+ T cells, IgG B cells, and IFN-γ-producing CD4+ T cells, exerting inflammatory and anti-tumor effects." (PMID 39199574, 2024). "By replenishing cDC1s within tumors we identified CD4+ T cells as critical effector cells driving tumor regression by polyclonal expansion." (PMID 39236156, 2024). "The therapeutic efficacy of “BC@Z-M + L” in tumor suppression was significantly impaired following the depletion of these T cell subsets, highlighting the essential roles of CD4/CD8 T cells in mediating the in vivo anti-tumor immune response." (PMID 39613774, 2024). "Subsequently, we employed flow cytometry to examine IFN-γ production by OT-1 CD8 T cells and endogenous CD8 T, CD4 T and NK cells infiltrating the tumor." (PMID 39629126, 2024). "E2F1 knockdown severely reduced these alterations in gene expression in both cell types to 1,462 (CD4+) and 1,708 (SK-Mel-47 E2F1-KD) DEGs, respectively, underlining the regulatory role of E2F1 in the crosstalk between tumor and immune cells." (PMID 39544930, 2024). "Of note, CD4+ helper T cells, B220+ B cells and F4/80+ macrophages also showed a trend towards increased tumor infiltration upon FLT1 blockade in the Brca1-def and Bard1-def models." (PMID 38956205, 2024). "To evaluate the opposing tumor immune effects of GzmB+ Treg vs GzmB+ Th cells, we determined the ratio of GzmB+FoxP3+/GzmB+FoxP- CD4 T cells." (PMID 38968186, 2024). "CD4+ T cells have an essential role in inducing the generation and maintenance of anti-tumor immune responses." (PMID 38349555, 2024). "Although the presence of PD1+ CD8+ T-cells was not changed, ceralasertib treatment induced a substantial increase in the expression of PD1 in the total population of tumor CD4+ T-cells as well as CD4+ CD44lo/- CD62L+ T effector cells." (PMID 38402224, 2024). "The IFN-I gene signature identified in tumor-infiltrating CD4+ T cells was also enriched in in vitro-CD3/CD28-activated CD4+ T cells." (PMID 38383773, 2024). "The in vivo tumor model showed an increased CD8+/CD4+ T cell ratio, indicating enhanced antitumor cytotoxicity." (PMID 39040921, 2024). "These CD4+ subsets can destroy autologous tumor cells ex vivo due to their secretion of TNF-α and IFN-γ." (PMID 39452154, 2024).
tumor (continued). "The variation in CD4+ T cells suggests that both helper and cytotoxic functions of CD4+ T cells contribute to tumor suppression." (PMID 39811730, 2024). "Biopsies revealed an increased number of tumor-infiltrating CD4+/CD8+ lymphocytes and a decrease in immunosuppressive Foxp3+ cells." (PMID 38473776, 2024). "The infiltration density of CD68+TAMs and CD4+FoxP3+Tregs in the tumor area of Mφ-Siglec-15+PD-L1+ patients were higher than that of Mφ-Siglec-15−PD-L1− patients (p < 0.05)." (PMID 38072971, 2024). "Taken together, these data suggest that B cells have only a limited capacity to induce CD4+ T cell proliferation to tumour antigens in vivo." (PMID 38125720, 2024). "Among these, T cells—including CD8+ T cells and CD4+ T cells—constitute the most abundant and distinctive immune cells within the tumor immune microenvironment." (PMID 39676861, 2024). "Second, the activity of tumor-infiltrating CD4+ and CD8+ T cells was significantly enhanced by the combined treatment of MβCD and cisplatin, to a similar extent enhanced by cisplatin treatment alone." (PMID 39343834, 2024). "We observed marked increase in CD8+ and CD4+ T‐cell population in post APG‐157 tumor biopsy in a recent phase I clinical trial." (PMID 38686626, 2024). "Mice that rejected large B78 tumors following CRI were rechallenged with B78 tumor cells and received either anti-CD4 mAb, anti-CD8 mAb, a mixture of anti-CD4/anti-CD8 mAb, anti-NK1.1 mAb or control rat IgG." (PMID 39076988, 2024). "Preclinical research has demonstrated that blocking IL-6 can inhibit tumor growth by enhancing the activity of CD4+/CD8+ effector T cells while suppressing Th17 and macrophages." (PMID 38304429, 2024). "Recent studies have emphasized the central role of CD4 T cells in peripheral tolerance, immunosuppression, and anti-tumor immunity." (PMID 38240686, 2024). "The mean tumor size was 3.8-fold and 10-fold larger respectively as compared to that of control group (CD4+-depleted p<0.0001, CD8+-depleted p<0.000001)." (PMID 39035008, 2024). "Mature DCs, when stimulated by tumor-associated antigens, can promote the proliferation and activation of CD8+ (cytotoxic T cells) and CD4+ T lymphocytes (helper T cells), which are involved with tumor apoptosis." (PMID 38549161, 2024). "The region highlighted by the white box shows the tumor margin and the inset images show staining and quantitation of CD4+ and CD8+ T-cells specifically in this region." (PMID 38204925, 2024). "Patients with NSCLC receiving neoadjuvant chemotherapy followed by surgery were found to have higher infiltrating levels of epithelial CD3 + CD4 + T lymphocytes and CD68 + epithelial and stromal tumor-associated macrophages than patients with prior surgery." (PMID 38468248, 2024). "On one hand, CD4+ T cells can differentiate into Th cells, which help to enhance other immune cells killing the tumour, and on the other hand, CD4+ T cells can differentiate into CD4+ CTL cells directly killing the tumour." (PMID 38801402, 2024). "The addition of anti-PD-1 did not significantly enhance the activation state of CD8+ T cells or CD4+ Teffs in the tumor at any of the time points examined." (PMID 38957315, 2024). "We found reduced circulating CD4+ and CD8+ T‐cells in tumour‐bearing mice compared with controls and RK more efficiently increased CD4+ T‐cells than CD8+ T‐cells." (PMID 38302863, 2024). "Mts1, presented on the CD3+CD4+ T-lymphocyte membrane, promotes the interaction of cytotoxic T-lymphocytes with the tumor cell membrane." (PMID 38928339, 2024). "The tumor-infiltrating CD4+ T cells in the TOFA-Th9 group contained more transferred cells than did those in the control Th9 group." (PMID 39187636, 2024). "It was found that the proportion of CD4+ T cells in mouse tumor tissues increased from 42.1% to 55.5% after NP4 treatment, while the proportion of CD8+ T cells increased from 19.0% to 28.9%." (PMID 39477929, 2024).
tumor (continued). "Increased CD-3 and CD-4 staining occurred in the tumor transplant area around the regions of tumor necrosis in immunocompromised TPV/∆66R/mIL-2 mice compared to immune-reconstituted TPV/∆66R/mIL-2 mice." (PMID 39200298, 2024). "Tumor infiltrating monocytes (TIMs) were divided into two populations based on CD4 expression; a division of monocytes unique to dogs." (PMID 38658617, 2024). "Tumor-specific T-cell responses as measured via systemic anti-HER2 CD4+ and CD8+ T cells pre- and post-treatment were increased with vaccination." (PMID 38803496, 2024). "The ratio of tumor-infiltrating CD4+ and CD8+ T cells was decreased after treatment with a low dose of cisplatin (1 mg/kg), although the ratio of total lymphocytes and T cells was slightly increased." (PMID 39343834, 2024). "The results showed that in the group with high CXCL10 expression, there were higher abundances of CD8 T cells, CD4 T cells, and M1 macrophages (p < 0.05), all of which play important roles in anti-tumor immune processes." (PMID 38720149, 2024). "The finding of increased infiltration of CD8+ and CD4+ cells in the untreated contralateral tumor supports the generation of a systemic response." (PMID 39409873, 2024). "IFN-γ plays an important role in anti-tumor immunity, and CD4+ T cells are the most important source of IFN-γ14." (PMID 38887597, 2024). "Recently, we identified CD4+ T cell neo-epitopes of this tumor by peptide elution from MC-38 cells induced to express MHC class II by transfection with the MHC class II transactivator (CIITA) gene." (PMID 39040850, 2024). "Decreased frequencies of both tumor-infiltrating CD4+ and CD8+ T cells were observed in the Id2fl/flCd4-Cre+ mice compared to the Id2fl/flCd4-Cre− mice." (PMID 38287103, 2024). "Further studies have revealed that TILs, such as CD8+ T cells and CD4+ T cells, including Foxp3+CD4+ T cells subset, are known to induce PD-L1 expression on tumour and immune cells in a number of types of cancers, including NSCLC." (PMID 38541208, 2024). "In cancer, interactions between the T cell receptor on CD8 + T cells with MHC-I–peptide complex and CD4 + T cells with MHC-II–peptide complex are key to establishing tumor-specific T cell responses and effective immunotherapy." (PMID 39160595, 2024). "CD3+, CD4+, and CD20+ lymphocytes were quantified by immunohistochemistry in paired pre‐ and post‐diagnostic benign prostate biopsy and tumor surgical specimens, respectively." (PMID 38523528, 2024). "Post thermal ablation seems to have beneficial effects on tumor progression and survival as it results in a higher number of CD4+ and CD8+ and a lower number of Treg cells and myeloid-derived suppressor cells." (PMID 39682081, 2024). "The observation that IL-12 increases the presence of OX40 (CD134) on the surface of CD4 T cells prompted the study of a combined anti-tumor capacity." (PMID 38474178, 2024). "In particular, we have investigated the abundance of antitumor immune cells in TILs evaluating CD3+ anti-tumour immune population, CD4+ helper and CD8+ cytotoxic T cell subsets." (PMID 38816839, 2024). "Cytotoxic CD8+ and helper/regulatory CD4+ T cells were detected by IHC, and the tumor shows high PD-1 and PD-L1 expression." (PMID 38605943, 2024). "SC134-TCB led to a 64% tumor growth inhibition, P = 0.0249, concomitant with a significantly increased CD4+ as well as CD8+ T-cell content." (PMID 39186309, 2024). "IL-6 produced by MDSCs can hinder the development and activity of CD4( +) T cells, ultimately promoting tumor development." (PMID 38717677, 2024). "The scores of CD3, CD4, CD8, and CD68 was assessed to know the degree of tumor infiltration lymphocytes (TILs) or tumor-associated macrophages (TAMs) infiltration, which was graded 0-12." (PMID 38370388, 2024). "Tumours treated with an attenuated Salmonella typhimurium strain (STm∆aroA) exhibited impaired activation of both CD4+ and CD8 + T cells." (PMID 39558103, 2024).
tumor (continued). "It is well known that effector T cells (including cytotoxic CD8+ T cells and effector CD4+ T cells), natural killer cells (NK), dendritic cells (DCs), and M1-polarized macrophages have anti-tumor effects." (PMID 38482210, 2024). "Spatial proteomics demonstrated increasing cell–cell connections between CD4+ T cells and Tregs in the tumor microenvironment, and distances between these cells became significantly shorter in the mid tumor regions compared to non-tumor regions." (PMID 38793588, 2024). "vvDD-IL-9 treatment significantly increased the number of tumor-infiltrating CD4+ T cells and CD8+ T cells, compared to parental virus vvDD treatment." (PMID 38473379, 2024). "The significance of MHC-II neoantigen presentation on tumor cells is likely to depend on the phenotype of the neoantigen-reactive CD4+ T cells." (PMID 39569190, 2024). "Tumor cells can also facilitate the production, activation, or function of immunosuppressive cells, such as CD4 + CD25+ regulatory T‐cells (T‐regs) or myeloid‐derived suppressor cells (MDSCs)." (PMID 39240588, 2024). "This suggests that the tumorigenic potential of FIA18 is augmented by escaping tumor-surveillance by CD4 T-cells and class I-restricted CD8+ cytotoxic T cells." (PMID 38215076, 2024). "Other work has shown that CD4+ T cells can target tumor cells independently of MHC-II by mobilizing or activating myeloid cells and NK cells." (PMID 39544936, 2024). "Initial findings from an animal study indicate that the administration of a DNA vaccine in conjunction with the LM vaccine resulted in a robust anti-tumor immune response mediated by CD4+ T cells." (PMID 39772046, 2024). "In the tumors from the untreated controls, there were visibly fewer CD8+, CD4+ T lymphocytes and eosinophils that managed to penetrate the tumor mass." (PMID 38524132, 2024). "To elucidate which major T cell subset is essential for tumor regression, we depleted CD4+ or CD8+ T cells from animals bearing PD-L2 KO pancreatic tumors, which were subsequently treated with doxorubicin." (PMID 38267628, 2024). "To delineate the immune context of LLT1TC high patients, we evaluated the distribution of CD4+ T cells, CD8+ T cells, Foxp3+ Tregs, CD68+ tumor‐associated macrophages, and CD19+ B cells." (PMID 38502058, 2024). "In a murine model of glioma, VISTA-deficient mice presented a significantly greater frequency of activated CD4+ T cells in tumors than did wild-type mice, suggesting an increase in tumor-specific T cells." (PMID 39482534, 2024). "This is done by stimulating CD8+ and CD4+ T cells to respond to tumor-specific antigens, such as HER2." (PMID 38256137, 2024). "It is well known that CD4+T cells can mediate the destruction of tumor cells by recognizing antigen presentation, activating CD8+T cells, and enhancing cytokine activity (Joyce & Fearon, 2015; Saha, Martuza & Rabkin, 2017; Wong, Bos & Sherman, 2008)." (PMID 38371373, 2024). "IL-16 is a pro-inflammatory cytokine that exerts chemotactic effects on CD4 T lymphocytes, monocytes, and eosinophils, playing a role in both the inflammatory response and tumor development." (PMID 38571956, 2024). "In nAg.Bhlhe40HiCd8, the top defining marker of this cluster was Bhlhe40, which we previously demonstrated was upregulated in tumor-specific T cells and required for CD4 and/or CD8 T cell effector function and response to ICT21." (PMID 38187708, 2024). "It is known that GI tumors lack MHC-I and MHC-II expression, which contributes to low CD8+ and CD4+ T cell tumor infiltration and poor prognosis." (PMID 38915093, 2024). "In contrast, a number of studies have shown that CD276 inhibits anti-tumor immunity, including suppression of CD4+ and CD8+ T cell activation and proliferation, and reduction of IL-2 and IFNγ production." (PMID 38637557, 2024). "“Professional” APCs and other MHC II-expressing tumor cells contribute to the initiation and maintenance of anti-tumor immunity through interaction with tumor-specific CD4+ T cells." (PMID 38818409, 2024).
tumor (continued). "IL-16 is a pro-inflammatory cytokine that recruits and activates immune cells such as CD4+ T cells, monocytes, and eosinophils, which can contribute to a tumor-promoting microenvironment." (PMID 39201599, 2024). "It is well known that patients with TNBC with greater tumor infiltrates of CD8+ than CD4+ have better outcomes following therapy." (PMID 39769460, 2024). "Then, tumors with MSI-H are highly infiltrated with cytotoxic T-cell lymphocytes like CD8 + T-cells with a Tc1 phenotype and CD4 + T-cells with a Th1 phenotype, to raise tumor-specific immune responses, which leads to sensitivity to ICI of MSI-H tumors." (PMID 38281914, 2024). "In contrast, non-irradiated melanoma cancer cell-derived exosome resulted in a semi-mature state of DCs, inhibiting T cell proliferation and IFN-γ production while increasing IL-10-producing CD4+ T cells, demonstrating weaker anti-tumor effects." (PMID 39174509, 2024). "mRNA-based cancer vaccines stimulate anti-tumor immunity, triggering antibody responses, B cell-mediated humoral reactions, and CD4+/CD8+ T cell responses." (PMID 39308511, 2024). "In bladder tumors, clonal expansion of cytotoxic CD4+ subsets are probably due to tumor antigen recognition." (PMID 39452154, 2024). "The subsets have specialized but also overlapping roles in the TME, including tumor antigen recognition, immune surveillance, cross-presentation, recruitment and activation of other immune cell types, and induction of tumor-specific CD4+ and CD8+ T cells." (PMID 39483484, 2024). "B. fragilis can also impair tumor formation and invasion by activating CD4 + T cells, thereby inducing the production of anti-inflammatory molecules such as IL-10." (PMID 38273292, 2024). "Loss of YAP1 in CD4+ and CD8+T cells enhanced T cell activation, differentiation, and cytotoxic function against tumor cells." (PMID 38550587, 2024). "Regarding the tumor immune phenotype, intratumoral CD4+ effector cells were increased in the combination group compared to the anti-PD-1 monotherapy group." (PMID 38170044, 2024). "The tumor microenvironment (TME) contains CD4+ T cells and CD8+ T cells, which predominantly act as effector cells in ICI therapy." (PMID 38569519, 2024). "The tumor cells communicated strongly with CD4+ T cells, CD8+ T cells, Tregs, macrophages and NK cells." (PMID 39474422, 2024). "FCM analysis also revealed that administration of the anti-CTLA-4 Ab increased CD4+ T cell infiltration into the tumor." (PMID 39106430, 2024). "HLA-DMB expression was negatively correlated with tumor purity and positively correlated with the infiltration levels of CD4+ T cells, CD8+ T cells, B cells, neutrophils, monocytes, myeloid dendritic cells, NK cells, and mast cells." (PMID 39917362, 2024). "Rather, the addition of MDMs to our multi-cellular models synergized toward enhanced tumor-directed CD4 and CD8 T cell trafficking, signifying a supportive role for TAMs in augmenting activated T cell homing toward tumor targets." (PMID 39414902, 2024). "Tumor‐infiltrating lymphocytes (TILs) such as CD4+ T cells, CD8+ T cells, innate immune cells including dendritic cells (DCs) and natural killer cells (NKs) are known to have a decisive impact on the characteristic of TME in GC." (PMID 38349050, 2024). "For instance, CD4+ helper T cells sustain the leukocytic anti-tumor functions through cytokine secretion (IFN-γ, TNF, and IL-2) while modifying the antigen presentation of DCs and B cells via direct CD40/CD40L interactions." (PMID 38673829, 2024). "Tumor tissues analysis for immune infiltration components revealed that PD and PR patients had higher levels of regulatory immunosuppressive T-cells (CD4+, FOXP3+) compared to CR patients." (PMID 39632825, 2024). "Recent studies have also revealed the cytotoxic capabilities of CD4+ T cells and their role in antigen recognition within the tumor immune microenvironment." (PMID 38887597, 2024).